DCAF7 (DDB1 and CUL4 associated factor 7)
Diseases named in the same sentence as DCAF7 in open-access papers (continued):
Sharing a sentence is not in itself a finding about the gene and the disease.
tumor (9 papers, 2008 to 2026). "Our results show that DNA‐methylation changes and copy‐number variations jointly drive aberrant DCAF7 expression, which is tightly linked to survival across tumour types." (PMID 41472554, 2026). "Single‐cell interrogation with CancerSEA showed that DCAF7 expression is positively associated with cell cycle progression and differentiation, but negatively linked to DNA repair and invasive signatures across aggregated tumour data." (PMID 41472554, 2026). "Here, for example, we can see that CEACAM6 has high expression in the smaller noninvasive tumor region at the bottom, while CDH2 (N-cadherin) and DCAF7 have high expression in the larger invasive tumor region at the top." (PMID 41160880, 2026). "Beyond DNA, RNA chemistry adds an additional regulatory tier: DCAF7 mRNA levels correlated positively with multiple modifiers of m1A, m5C and m6A across tumours." (PMID 41472554, 2026). "Inverted microscopy indicated evident tumour cell lysis in the DCAF7‐knockout group, which became more pronounced with higher effector‐to‐target (E:T) ratios." (PMID 41472554, 2026). "Gene‐set enrichment analysis (GSEA) further demonstrated activation of cell‐cycle, Wnt, E2F and Hippo signalling in DCAF7‐amplified tumours." (PMID 41472554, 2026). "Multi‐omics datasets (genomic, transcriptomic, epigenomic, proteomic and single‐cell) from 33 tumor types were integrated to define DCAF7 expression, regulation, and clinical significance." (PMID 41472554, 2026). "Focusing on LIHC, stratification of TCGA tumours by DCAF7 level identified 1612 differentially expressed genes (DEGs), of which 1244 were up‐regulated and 368 down‐regulated in the high‐expression group." (PMID 41472554, 2026). "Single‐cell RNA‐seq from Tumor Immune Single‐cell Hub (TISCH) revealed preferential DCAF7 expression in proliferating T cells (T prolif) across three LIHC datasets (GSE140228_10X, GSE140228_Smartseq2 and GSE98638)." (PMID 41472554, 2026). "Together, these results position DCAF7 as a central regulator of oncogenic signalling and tumour immunity with translational potential." (PMID 41472554, 2026). "Single‐cell and bulk immune‐deconvolution analyses demonstrate that DCAF7 reshapes the tumour immune microenvironment, altering T cell subsets and immune‐checkpoint expression." (PMID 41472554, 2026). "Mechanistic interrogation in LIHC further reveals that YTHDC1 enhances m6A methylation of DCAF7 mRNA, leading to increased DCAF7 expression, which in turn amplifies Wnt/β‐catenin signalling and promotes tumour proliferation and migration." (PMID 41472554, 2026). "Previous studies have demonstrated that DCAF7 can regulate apoptosis and other pathways to inhibit tumor cell growth." (PMID 40877242, 2025). "Third, DCAF7 protein levels were also higher in HCC tumor tissues than in normal tissues from the CPTAC proteomic database." (PMID 40877242, 2025). "mRNA expression of target genes Entpd1 in tumor and Dcaf7 in liver was reduced indicating biological activity of INT-1B3." (PMID 39007281, 2024). "In the subcutaneous xenograft mouse model, knockdown of DCAF7 significantly enhanced cisplatin sensitivity, leading to reduced tumor size and weight in cisplatin‐treated mice." (PMID 38973296, 2024). "Analysis of GDSC profiles revealed that tumours with high DCAF7 expression tend to be more responsive to several cytotoxic and targeted agents, indicating that DCAF7 could serve as a predictive marker of chemotherapy sensitivity." (PMID 41472554, 2026). "Using TIMER2.0, we correlated DCAF7 expression with six immune lineages across 33 TCGA tumours." (PMID 41472554, 2026). "Consistent with these bioinformatic predictions, our HepG2–T cell co‐culture assays demonstrated that DCAF7 knockout markedly enhanced CD8+ T cell‐mediated cytotoxicity and IFN‐γ secretion, providing functional evidence that DCAF7 restrains anti‐tumour immune activity within the TME." (PMID 41472554, 2026).
tumor (continued). "Immunogenomic analyses linked high DCAF7 to CD4+ T‐cell enrichment, broad upregulation of checkpoint genes (PD‐1/PD‐L1, CTLA‐4, TIGIT), and increased tumour mutational burden, microsatellite instability and neoantigen load, suggesting an immune‐evasive phenotype." (PMID 41472554, 2026). "However, the combination of DCAF7 knockdown with cisplatin markedly enhanced the tumor growth inhibition, achieving a TGI of 74.63% (P < 0.001) in NPC in vivo at the termination of the experiment." (PMID 38973296, 2024). "Together, these data suggest that m6A deposition on DCAF7 mRNA and its recognition by YTHDC1 cooperatively enhance DCAF7 expression, thereby linking RNA methylation machinery to oncogenic signalling in LIHC and potentially other tumour types." (PMID 41472554, 2026). "MAX, DCAF7, and STMN1 were identified as novel targets of miR-193a, which may contribute to its anti-tumor effect." (PMID 37443682, 2023). "MAX, DCAF7, and STMN1 were identified as novel targets of miR-193a that could contribute to its tumor-suppressive effect." (PMID 32410663, 2020). "In LIHC, DCAF7 correlated strongly with PD‐1/PD‐L1 and CTLA‐4 expression, implying that tumours with elevated DCAF7 might preferentially exploit checkpoint pathways for immune evasion and could therefore benefit from dual targeting of DCAF7‐driven signalling and checkpoint blockade." (PMID 41472554, 2026). "Indeed, DCAF7 knockdown significantly enhanced sorafenib sensitivity and dramatically suppressed Huh7 xenograft tumor growth in vivo, without altering the mouse body weight." (PMID 40877242, 2025).
infection (5 papers, 2014 to 2025). The state of being infected such as from the introduction of a foreign agent such as serum, vaccine, antigenic substance or organism. "Three of these genes (Dcaf7, Dusp3, and Psme3) were down-regulated in susceptible vs. resistant mice at both pre- and post-infection time points by qPCR." (PMID 24901344, 2014). "Five genes in the QTL (Dcaf7, Dusp3, Fam134c, Psme3, and Slc4a1) were significantly differently expressed in a) susceptible vs. resistant mice, and b) humans with S. aureus blood stream infection vs. healthy human subjects." (PMID 24901344, 2014). "Next, the control and DCAF7-expressing A549 cells were infected with the H1N1 (MOI = 0.1) and H3N2 viruses (MOI = 0.2), expression of DCAF7 significantly reduced NP protein levels of both viruses and viral growth at the indicated infection time points." (PMID 40145735, 2025). "Subsequently, the mRNA and protein levels of DCAF7 were detected at different time points post-infection." (PMID 40145735, 2025). "The restoration of DCAF7 expression also reduced viral NP protein and RNA levels in DCAF7 knockout cells compared with the control cells at the indicated infection time points." (PMID 40145735, 2025). "Although our study has concentrated on boosting TFEB levels during infection, the efficacy of DCAF7 inhibitors to modulate TFEB activity under basal conditions suggests potential application of this approach for other, noninfectious conditions associated with impaired autolysosomal activity." (PMID 40465712, 2025). "Whether the influenza A virus attenuates its antiviral ability by regulating the expression of DCAF7 during infection." (PMID 40145735, 2025). "Our host-targeted small molecule DCAF7 inhibition therapy, which showed efficacy against SARS-CoV-2 in cell and animal-based infection models, can likely supplement current antiviral approaches." (PMID 40465712, 2025). "Silencing DCAF7 increased the NP protein expression and virus titers of H1N1 and H3N2 viruses in A549 cells at the indicated infection time points." (PMID 40145735, 2025). "Knockdown of DCAF7 had a relatively minimal effect on suppression of IFI6, IFIT1, OAS1&2 while affecting IFIT2 slightly more with HAdV-B7 infection." (PMID 38940561, 2024). "DCAF7-overexpressing A549 cells or DCAF7-silenced A549 cells were infected with the H1N1 virus, then the NP vRNA, cRNA, and mRNA abundance were detected at the indicated infection time points by qRT-PCR." (PMID 40145735, 2025).
DCAF7 also shares sentences with these, for which no sentence is quoted: pancreatic neuroendocrine tumor (2 papers); cholangiocarcinoma (1); cleft palate (1); colon adenocarcinoma (1); endocervical adenocarcinoma (1); inflammatory bowel disease (1); lung squamous cell carcinoma (1); mesothelioma (1); Obesity (1); Pan (1); pancreatic adenocarcinoma (1); prostate adenocarcinoma (1); rectum adenocarcinoma (1); sarcoma (1); skin cutaneous melanoma (1); stomach adenocarcinoma (1); ulcerative colitis (1); uterine corpus endometrial carcinoma (1); uveal melanoma (1).